BRCA2 (BRCA2 DNA repair associated)
Diseases named in the same sentence as BRCA2 in open-access papers (continued):
Sharing a sentence is not in itself a finding about the gene and the disease.
cancer (continued). "Consistent with prior studies, we found these higher rates associated with homozygous deletions at the BRCA2 locus that often spans the proximal RB1 that is a common lineage-specific driver in these cancer types." (PMID 36418296, 2022). "Investigations of the genetic features of PDAC have demonstrated a frequent occurrence of mutations in genes involved in homologous recombination (HR), especially in the breast cancer susceptibility gene 2 (BRCA2)." (PMID 36358659, 2022). "In the Irish Travelling community, for example, genetic variants associated with cancer susceptibility have been noted, namely BRCA2 alterations." (PMID 35933387, 2022). "BRCA1 and BRCA2 PV carriers are also known to have excessive risk to develop contralateral cancer 20 years after their initial cancer diagnosis." (PMID 35323371, 2022). "The etiology of cancer-causing mutations in BRCA2 is complex with both germline and somatic mutations spanning the entire length of the protein." (PMID 36098506, 2022). "Four PARP inhibitors have been approved for the treatment of BRCA1- or BRCA2-deficient cancers, leading to promising clinical responses." (PMID 35349716, 2022). "Cells with a defect in any component of HR are sensitive to treatment with PARP inhibitors, as exploited therapeutically in cancers where BRCA1 or BRCA2 are mutated." (PMID 35468497, 2022). "Our recent work suggests that CSB facilitates BIR-mediated restart of stalled forks and that this function of CSB promotes survival of cancer cells with deficiencies in either BRCA1 or BRCA2 in response to replication stress." (PMID 36142121, 2022). "For large-scale testing of BRCA2 VUS to be successful in predicting cancer risk, we need to carefully consider which specific functions impart tumor suppression." (PMID 36098506, 2022). "In the literature there are several studies of mutation in the BRCA1 and BRCA2 genes and association with different cancers." (PMID 35395863, 2022). "One mechanism that has been confirmed in patients with BRCA1- or BRCA2-mutated cancers is the occurrence of secondary mutations in the BRCA1 or BRCA2 genes, leading to HR restoration." (PMID 36467895, 2022). "Pathogenic variants in BRCA1 and BRCA2 are associated with an increased risk of several cancers, including breast and ovarian cancer." (PMID 33469799, 2022). "Germ-line mutation of the breast cancer susceptibility gene, BRCA2, predisposes carriers to cancers of the breast, pancreas, ovary, and other tissues." (PMID 35697743, 2022). "With the adoption of a larger 30 genes panel in our previous study, 15 probands that carried uncertain significance (Class 3) BRCA1 and BRCA2 variants were found to carry mutations in other cancer predisposition genes with high to moderate penetrance." (PMID 35641994, 2022). "Of the metastatic subgroup (M1, n = 34), mean PSA was significantly lower in BRCA2 mutated cancers than wild-type (p = 0.018)." (PMID 36362213, 2022). "Increased cancer susceptibility in the fallopian tube appears to begin with loss of a single allele of BRCA1 or BRCA2." (PMID 35159349, 2022). "BRCA1/BRCA2 screening offers an opportunity for primary prevention of cancer in unaffected carriers by risk-reducing mastectomy (RRM) and RRSO." (PMID 36551598, 2022). "We therefore propose that BRCA2 isoform switching represents a tumorigenic driver in BRCA1/2 mutation-associated cancers." (PMID 36344544, 2022). "According to the literature, RAD51 rs1801320 was also associated with increased risk for breast and other cancers, especially in carriers of BRCA2 mutations." (PMID 36139526, 2022). "In this systematic review it was found that the effect direction of mutations in BRCA1 and BRCA2 genes varies by cancer type." (PMID 35444210, 2022). "BRCA1 c.5407-25T>A was identified in siblings both having OC (one diagnosed with a HGSC of the ovary and the other with primary peritoneal carcinomatosis), cancer phenotypes consistent with harboring a BRCA1 or BRCA2 pathogenic variant." (PMID 35456503, 2022).
cancer (continued). "Pathogenic mutations in the BRCA2 tumor suppressor gene predispose to breast, ovarian, pancreatic, prostate, and other cancers." (PMID 36098506, 2022). "The collaboration between all the diagnostic genetic laboratories in Norway will be extended to include variant interpretation of several other cancer genes like BRCA2 and the MMR genes." (PMID 34981296, 2022). "The excess mutational load in BRCA1–/– cells follows a specific pattern of base changes, with strong correlation to COSMIC signature SBS3, a hallmark phenotype of BRCA1 or BRCA2 mutated human cancers." (PMID 35130276, 2022). "Following the initial discovery of synthetic lethality between PARP inhibition and BRCA1 or BRCA2 deficiency, other cancer types that harbor mutations in genes functioning in the DDR and DNA repair networks were also shown to be sensitive to PARP inhibition." (PMID 35022408, 2022). "As germline and tumor sequencing endeavors become incorporated into clinical cancer care, findings of missense variants, such as BRCA2 R3052W, with potentially uncertain functional consequences will be encountered more frequently." (PMID 35711920, 2022). "Clinical testing for pathogenic variants in BRCA1 and BRCA2 has been established in clinical settings as it has been proven to improve cancer risk assessment and management of carriers." (PMID 35456503, 2022). "Physicians treating patients with cancer should be alert of the FANCD1/BRCA2 and FANCN/PALB2 associated malignancies and consider the possibility of FA diagnosis." (PMID 36091172, 2022). "In vitro, the exposure of BRCA1 and BRCA2 mutated cancer cells to cisplatin or PARPis favors the development of secondary genetic changes on the mutated allele which restore a functional protein and confer platinum and PARPis resistance." (PMID 35326571, 2022). "Distribution of BRCA1 and BRCA2 pathogenic variants tested in the National Cancer Control Programme of the Ministry of Health for the years 2018–21 (n = 3,458)." (PMID 36171877, 2022). "If this is a pathogenic variant in BRCA1 or BRCA2, the cells in the body harbouring the variant will have a predisposition to associated cancers." (PMID 36068545, 2022). "In this study, the frequency of co-occurring variants in both the BRCA1 and BRCA2 genes in the pan-cancer cohort was approximately 3%, which was somehow higher than that of most previous studies." (PMID 36147908, 2022). "Unfortunately, early embryonic lethality in mouse models for cancer-associated genes such as BRCA2 is a confounding factor." (PMID 35042909, 2022). "The tumor suppressor gene BRCA2 exemplifies this conundrum: while BRCA2 mutation is associated with cancer susceptibility in humans and animals, mouse models with homozygous Brca2 mutation exhibit early embryonic lethality." (PMID 35042909, 2022). "Though BRCA1 and BRCA2 are associated with cancer risk, tumors that are identified as having “BRCAness” appear to be susceptible to specific therapeutic approaches." (PMID 35626055, 2022). "BRCA2 mutation carriers of cancer have different clinicopathological features, chemotherapeutic drug sensitivity, and targeted therapy in cancer patients with no mutations." (PMID 36397405, 2022). "Recently, the PARP inhibitor Olaparib has been evaluated as a promising anti-cancer agent in women with germline pathogenic variants in BRCA1 or BRCA2." (PMID 35563522, 2022). "These divergent effects exemplify the often-paradoxical outcomes that occur in embryos (embryonic lethality) versus adult animals (cancer predisposition) with mutations in cancer susceptibility genes such as BRCA2." (PMID 35042909, 2022). "Identifying carriers of pathogenic BRCA1/BRCA2 variants reduces cancer morbidity and mortality through surveillance and prevention." (PMID 36551598, 2022). "Olaparib is the first FDA approved PARP small molecule inhibitor for BRCA1- and BRCA2-mutated cancers." (PMID 35328658, 2022).
cancer (continued). "Although commonly grouped together in most datasets, BRCA1 and BRCA2 have several differentiating roles in cell function as well as different implications for cancer risk and treatment response across tumour types." (PMID 36497408, 2022). "BRCA status can impact on preventive options according to the cancer spectrum related to BRCA1 or BRCA2 pathogenetic variants." (PMID 35454911, 2022). "Another centrosomal protein that is cleaved by MT1-MMP is the breast cancer type 2 susceptibility gene (BRCA2), which indicates a potential role of MT1-MMP in regulating BRCA2 trafficking and genome stability in HeLa, S3, U2OS and MCF7 cells." (PMID 36076910, 2022). "RAD51 and BRCA2 are two key HR players and are strongly associated with cancer onset and anticancer therapies." (PMID 35955488, 2022). "Since HRD and inhibition of PARP are synthetically lethal, cancer patients carrying BRCA1 or BRCA2 mutations benefit from PARP inhibitor therapy." (PMID 35159019, 2022). "Our findings, based on actual expenditures from healthcare systems, indicate the advantage in expanding use of genetics for identification of women who are BRCA1/BRCA2 carriers, thus at high risk for developing cancer." (PMID 36551598, 2022). "The breast cancer susceptibility genes BRCA1 and BRCA2 (BRCA genes) are well-known tumor suppressors whose inactivation increases the probability of developing cancer, particularly of breast and ovarian origin, but also in the pancreas and prostate." (PMID 36969741, 2022). "If a genetic test reveals a germline pathogenic variant in a cancer predisposition gene such as BRCA1 or BRCA2, family members also become eligible for a genetic test." (PMID 34617209, 2022). "First, we show that both approaches can identify genetic modifications that alter PARylation levels, such as hyper-PARylation in BRCA2-deficient cancer cells." (PMID 35954352, 2022). "Phenotypic variability that depended on the type of BRCA2 mutation and family ethnicity has been documented in a study evaluating the incidence of 7 cancer types in 440 families from various countries." (PMID 35761384, 2022). "This case-control study examines the association of BRCA1 and BRCA2 pathogenic variants with additional cancer types and their clinical characteristics in 100 914 Japanese individuals across 14 cancer types." (PMID 35420638, 2022). "An important next step will be to determine why a particular microenvironment promotes cell proliferation and subsequent cancer initiation in the context of heritable BRCA2 mutation." (PMID 35042909, 2022). "Future studies will reveal the cancer risk in individuals carrying BRCA2 L2510P and other variants that disrupt this interaction and are considered HR-deficient." (PMID 35365640, 2022). "The silenced BRCA1 and/or BRCA2 have been associated with the deficiency in the DNA double-strand repair and genomic instability, leading to cancer predisposition." (PMID 36160115, 2022). "In line with the idea that cancer cells with pathogenic BRCA mutations depend on TPX2, knockdown of TPX2 has been reported to lead to HR defects and reduced viability of BRCA2-deficient cancer cells." (PMID 36350633, 2022). "PARPis have been approved by the U.S. Food and Drug Administration (FDA) and the European Medicines Agency (EMA) for the treatment of several cancers with BRCA1/BRCA2 mutations, or other deficiencies in HR components." (PMID 36361678, 2022). "In this regard, synthetic lethality is proven a promising strategy to inhibit cancer cells that harbor deficient BRCA1 or BRCA2 genes." (PMID 35328658, 2022). "In 2003, indications of PGT wereextended to late-onset or incomplete penetrance diseases, such as hereditary predisposition to cancer as BRCA1 or BRCA2 mutations." (PMID 36497251, 2022). "Their loss of function easily leads to genetic instability, leading to a varying degree of increased cancer risk in BRCA2 mutation carriers compared with the general population." (PMID 36397405, 2022).
cancer (continued). "In families with BRCA2 mutations in which one member had an early onset of PC (< 50 years of age), the risk of this cancer in subsequent generations was estimated to be 9.9 times higher than that in the general population." (PMID 35761384, 2022). "When further examining associations between various clinical variables and deleterious gene mutations within each cancer subtype, we found that BRCA2 mutations were more prevalent in patients in HR+, Her2- and TNBC subtype patients." (PMID 35494038, 2022). "BRCA1 and BRCA2 are good examples of genes whose loss promotes cancer development but also make the cancer cell vulnerable to DNA damage." (PMID 36189922, 2022). "Generally, cancer patients with the BRCA2 mutations were reported to have a more aggressive phenotype compared to those with FANCD2 mutation." (PMID 36686473, 2022). "Carriers of deleterious heterozygous germline mutations in the BRCA1 and BRCA2 genes have high risk of different types of cancer, such as PCa." (PMID 35740437, 2022). "Among cancer predisposing genes, mutations in BRCA2 and ATM play a role in PDAC progression, whilst the role of other genes remains to be defined." (PMID 35805011, 2022). "Truncated C-terminus RAD52 alleles have been previously shown to suppress certain germline BRCA2 mutations and the E320* RAD52 truncation also co-occurs with BRCA2 mutations in human cancers." (PMID 36530474, 2022). "The highest number of variants was found in the following genes: BRCA1 (52.9%; 45/85) with the most common variant p.Gln1756ProfsTer74 in 26.7% (12/45), BRCA2 (22.4%; 19/85) and other cancer associated genes constituting 24.7% (21/85) of variants." (PMID 36290365, 2022). "Olaparib has been approved as a therapeutic agent for cancer patients harboring BRCA1/BRCA2 mutations." (PMID 35563432, 2022). "eFigure 7 in the Supplement describes associations between the carrier status in BRCA1 and BRCA2 for cases with a diagnosis of the 7 associated cancers and reported family history of each of these cancer types." (PMID 35420638, 2022). "Five patients harboring a programmed death ligand 1/2 (PD-L1/-L2) amplification, TMB-high, breast cancer gene 2 (BRCA2) mutation or ERBB2 amplification were treated with each investigational drug." (PMID 36119486, 2022). "The results of this large-scale registry-based case-control study suggest that pathogenic variants in BRCA1 and BRCA2 were associated with the risk of 7 cancer types." (PMID 35420638, 2022). "Several families in the BIC database with evidence of genetic linkage indicate that the BRCA2 R3052W variant is a pathogenic mutation with a high probability of future cancer risk." (PMID 35711920, 2022). "Genetic loci associated with other cancers and cancer syndromes, including BRCA2 and PALB2, are also associated with PDAC." (PMID 36077772, 2022). "Germline mutations in BRCA1 and BRCA2 are well studied and associated with a high risk of cancer, particularly breast and ovarian cancers, with high hereditary penetrance in an autosomal dominant pattern." (PMID 35668531, 2022). "Rahul is a 40-year-old man who had a test via a genetics clinic for the cancer-predisposing BRCA2 variant identified in his aunt." (PMID 34649841, 2021). "In conclusion, our data indicate that curcumin, which has RAD52 inhibitor activity, is a promising candidate for sensitizing BRCA2-deficient cells to DNA damage-based cancer therapies." (PMID 33922657, 2021). "When hyperthermia is used to inhibit the HR pathway, BRCA2-deficient cancer cells become more sensitive to radiation treatment." (PMID 34238917, 2021). "Germline mono-allelic mutations in the tumor suppressor genes BRCA1/2 (breast cancer susceptibility gene 1/2) predispose to breast and ovarian cancer, and in the case of BRCA2, also confer moderate risk to other cancers such as pancreatic and prostate cancer." (PMID 34359619, 2021).
cancer (continued). "A limitation to the study is that we have only tested synthetic lethality in BRCA2 or ATM deficient HeLa cancer cell line models." (PMID 34373746, 2021). "Treatment of cancer in BRCA2-associated FA has been disappointing and the reported survival is poor." (PMID 34680915, 2021). "It turned out that BRCA1 and BRCA2 are quite exceptional in their high penetrance, with most cancer predisposition genes showing only mild effects." (PMID 34290314, 2021). "Germline mutations in BRCA1 or BRCA2 tumour suppressor genes predispose to different cancers, as does oncogene activation." (PMID 34389725, 2021). "These two indel patterns have also been described previously in BRCA2-deficient human cancer biopsies." (PMID 34145376, 2021). "Due to its role in cancer initiation and progression, BRCA2 loss of function variants play a key role in determining patient prognosis and treatment patterns." (PMID 33503928, 2021). "Previous reports have demonstrated that women carrying a pathogenic mutation in the BRCA1 or BRCA2 genes have an increased risk of developing a second primary cancer in the contralateral breast." (PMID 34490083, 2021). "Five pathogenic variants (two in BRCA1 and three in BRCA2) were present only in general population with five carriers, and three BRCA2 pathogenic variants were present in both general population and the cancer cohort with six carriers." (PMID 34235180, 2021). "Studies have demonstrated that inhibition of RAD52 gene function in BRCA2-deficient cancer causes synthetic lethality, suggesting a potential application of RAD52 in cancer-targeted therapy." (PMID 33995041, 2021). "In total, 29 germline pathogenic/likely pathogenic variants were identified in autosomal dominant cancer predisposition genes where the gene was pertinent to the cancer family history (including BRCA1/BRCA2, the mismatch-repair genes and APC)." (PMID 33654310, 2021). "Here, we demonstrate that WRN helicase ensures efficient restart and limits excessive degradation of stalled forks in BRCA2-deficient cancer cells." (PMID 34772932, 2021). "For example, for cancers caused by certain BRCA2 mutations, specific antisense oligonucleotides (ASO) have been shown to block cryptic exon inclusion caused by deep intronic mutations in vitro." (PMID 34276779, 2021). "Patients diagnosed with cancer and for whom a germline or somatic pathogenic BRCA2 mutation is found often respond well to chemotherapy agents such as PARPi and platinum drugs." (PMID 34065235, 2021). "The frequency of germline BRCA1/2 gene mutation carriers and the ratio of germline BRCA1 to BRCA2 mutations in BRCA-related cancer patients vary depending on the population." (PMID 34356066, 2021). "BRCA2 mutation frequency was 12.5% (9 of 72) in our data set and similarly distributed across cancer cohorts (HGSC: 0/19, TNBC: 1/21, HGSC 2/21, MM: 2/12, and Mixed: 4/28)." (PMID 34446728, 2021). "Translational research performed in SA involving the highly penetrant BRCA1 and BRCA2 cancer susceptibility genes has identified various recurrent and founder variants as targets for both pharmacogenetic and cascade testing across population groups." (PMID 34660253, 2021). "These compounds would be particularly interesting for the treatment of cancers with mutations in some DNA repair factors such as BRCA1 or BRCA2, which have been shown to protect the genome from FA1,5." (PMID 33495466, 2021). "The Catalog Of Somatic Mutations in Cancer (COSMIC) reports 312 somatic BRCA2 mutations from 4093 samples tested across all subtypes of PCa, a percentage prevalence of 7%." (PMID 34830851, 2021). "Synthetic lethality is a novel paradigm in cancer treatment regimens that combines a cancer-inherent genetic mutation (such as BRCA1 or BRCA2 mutation) with the pharmacological inhibition of a specific molecular target (such as PARP1)." (PMID 34572428, 2021).